TMEM95 (transmembrane protein 95)
Description:
Sperm protein required for fusion of sperm with the egg membrane during fertilization.
Synonyms: MGC129793; UNQ9390
Tractability: Antibody: UniProt predicts a signal peptide or a membrane-spanning region.
Gene: Protein-coding gene on chromosome 17 (7,355,123 to 7,357,219, forward strand). Ensembl gene ENSG00000182896.
Subcellular location: Cytoplasmic vesicle, secretory vesicle, acrosome membrane
Gene Ontology:
Molecular function: protein binding
Biological process: fusion of sperm to egg plasma membrane involved in single fertilization
Cellular component: acrosomal membrane; sperm plasma membrane
Genetic constraint (gnomAD): Loss-of-function variants: 22 observed, 26.11 expected, observed/expected ratio (o/e) 0.84, 90% interval 0.6 to 1.2. The upper end of that interval is the gene's LOEUF score, 1.2, which puts it in group 5 of 6, group 1 being the genes least tolerant of losing a copy. Missense variants: 203 observed, 217.72 expected, observed/expected ratio (o/e) 0.93, 90% interval 0.83 to 1.05. Synonymous variants: 77 observed, 84.4 expected, observed/expected ratio (o/e) 0.91, 90% interval 0.76 to 1.1.
Homologues: Orthologues: macaque TMEM95 (93% identical), chimpanzee TMEM95 (81% identical), rabbit TMEM95 (76% identical), pig TMEM95 (74% identical), guinea pig TMEM95 (74% identical), dog TMEM95 (69% identical), mouse Tmem95 (65% identical), rat Tmem95 (61% identical).
Diseases named in the same sentence as TMEM95 in open-access papers:
TMEM95 is named in the same sentence as 5 diseases in open-access papers, as found by Europe PMC text mining. Sharing a sentence is not in itself a finding about the gene and the disease. The quoted sentences say what the papers report.
Infertility (4 papers, 2020 to 2024). "Subsequently, we tested whether gamete membrane fusion was the only process involved in the infertility of Tmem95-deficient male mice." (PMID 32484434, 2020). "TMEM95 ablation in mice caused complete male-specific infertility." (PMID 32484434, 2020). "Eight genes that result in male infertility (IZUMO1, SPACA6, TMEM95, TMEM81, SOF1, FIMP, DCST1, and DCST2) and an additional two that cause infertility in females (JUNO and CD9) have been identified." (PMID 38381819, 2024). "Our work suggests avenues for the identification of the TMEM95 egg receptor and the development of infertility treatments and contraceptives for humans." (PMID 36161911, 2022). "Although these data point at a number of potential molecular targets only three causative mutations, resulting in male sub- or infertility in cattle have been determined in the FSHB, TMEM95, and ARMC3 gene hitherto." (PMID 31963602, 2020).
Arrhythmia (1 paper, 2024). Any cardiac rhythm other than the normal sinus rhythm. "Eight of these associations were novel (LMNA, SMAD6, HSPB9, TMEM95, KLF1, TET2, NME3, KDM5B) and 5 genes have previously been linked to arrhythmias (SCN5A, TTN, RPL3L, PKP2, PMVK)." (PMID 38390584, 2024).
conduction disorders (1 paper, 2024). "Rare variations in 5 genes were linked to conduction disorders (SCN5A, LMNA, SMAD6, HSPB9, TMEM95)." (PMID 38390584, 2024).
TMEM95 also shares sentences with these, for which no sentence is quoted: male infertility (2 papers); heart conduction disorders (1).